PTGDR (prostaglandin D2 receptor)
Description:
Receptor for prostaglandin D2 (PGD2). The activity of this receptor is mainly mediated by G(s) proteins that stimulate adenylate cyclase, resulting in an elevation of intracellular cAMP. A mobilization of calcium is also observed, but without formation of inositol 1,4,5-trisphosphate (By similarity). Involved in PLA2G3-dependent maturation of mast cells. PLA2G3 is secreted by immature mast cells and acts on nearby fibroblasts upstream to PTDGS to synthesize PGD2, which in turn promotes mast cell maturation and degranulation via PTGDR (By similarity).
Synonyms: DP; DP1; PTGDR1; AS1; ASRT1
Tractability: Small molecule: an approved drug acts on it; a high-quality ligand is known; it belongs to a druggable protein family. Antibody: UniProt places it where antibodies can reach, with high confidence; its Gene Ontology location is reachable by antibodies, with high confidence; UniProt predicts a signal peptide or a membrane-spanning region; the Human Protein Atlas places it where antibodies can reach. PROTAC: a small molecule that binds it is known.
Target class: Lipid-like ligand receptor (family A GPCR); Membrane receptor; Prostanoid receptor; Small molecule receptor (family A GPCR); Family A G protein-coupled receptor
Chemical probes: CHEMBL383484, CHEMBL483991
Gene: Protein-coding gene on chromosome 14 (52,267,698 to 52,276,724, forward strand). Ensembl gene ENSG00000168229.
Subcellular location: Cell membrane
Subcellular location (Human Protein Atlas): Cytosol; Plasma membrane
Pathways (Reactome):
Signal Transduction: G alpha (s) signalling events; Prostanoid ligand receptors
Gene Ontology:
Molecular function: protein binding; prostaglandin D receptor activity; G protein-coupled receptor activity; prostaglandin J receptor activity
Biological process: cellular response to prostaglandin D stimulus; G protein-coupled receptor signaling pathway; inflammatory response; positive regulation of cytosolic calcium ion concentration
Cellular component: plasma membrane; membrane
Genetic constraint (gnomAD): Loss-of-function variants: 24 observed, 22.14 expected, observed/expected ratio (o/e) 1.08, 90% interval 0.78 to 1.52. The upper end of that interval is the gene's LOEUF score, 1.52, which puts it in group 6 of 6, group 1 being the genes least tolerant of losing a copy. Missense variants: 526 observed, 488.26 expected, observed/expected ratio (o/e) 1.08, 90% interval 1 to 1.16. Synonymous variants: 267 observed, 223.96 expected, observed/expected ratio (o/e) 1.19, 90% interval 1.08 to 1.32.
Homologues: Orthologues: chimpanzee PTGDR (99% identical), macaque PTGDR (94% identical), dog PTGDR (82% identical), pig PTGDR (81% identical), rat Ptgdr (76% identical), rat Ptgdrl1 (76% identical), guinea pig PTGDR (75% identical), mouse Ptgdr (73% identical), rabbit PTGDR (64% identical), tropical clawed frog PTGDR (43% identical). Paralogues in human: PTGER2 (41% identical), PTGIR (37% identical), PTGER4 (31% identical), PTGER3 (25% identical), TBXA2R (23% identical), PTGER1 (23% identical), PTGFR (21% identical).
Diseases named in the same sentence as PTGDR in open-access papers:
PTGDR is named in the same sentence as 138 diseases in open-access papers, as found by Europe PMC text mining. Sharing a sentence is not in itself a finding about the gene and the disease. The quoted sentences say what the papers report.
breast carcinoma (36 papers, 2016 to 2026). "The Prostaglandin D2 Receptor (PTGDR) also called PGD2 has been associated with different type of cancers even though its role in breast cancer has not been well described." (PMID 38038766, 2024). "Furthermore, a previous study found that a risk model composed of PTGDR, PNOC and CCL23 was helpful in predicting the prognosis of HER2-positive breast cancer, and that patients with low risk scores may benefit from immunotherapy." (PMID 41383978, 2026).
lung cancer (35 papers, 2014 to 2025). A malignant neoplasm involving the lung. "Lewis lung cancer cells implanted onto the backs of mice lacking the PGD2 receptor (PTGDR, also known as DP1), grew faster than tumors implanted onto wild-type mice." (PMID 24729479, 2014).
asthma (26 papers, 2005 to 2025). "A total of 250,000 asthma-related deaths are recorded annually and several proteins including chymase, spleen tyrosine kinase, and prostaglandin D2 receptor have been implicated in the pathophysiology of asthma." (PMID 37947895, 2023). "Functional studies suggest that promoter polymorphisms of the Prostaglandin D Receptor (PTGDR) gene can be involved in asthma." (PMID 30986261, 2019). "In recent years, certain polymorphisms and specific haplotypes and diplotypes of the promoter region of PTGDR have been associated to allergy and asthma." (PMID 29088248, 2017). "Although not previously connected to RA, several of these genes were recently shown to be implicated in autoimmunity (e.g. CARD6 in psoriasis, PTGDR in asthma, BPI in cystic fibrosis) and immune-related processes." (PMID 28148290, 2017). "The third most important association with asthma was found with rs803010 (P = 4.4 × 10−4) located in the promoter of the prostaglandin D2 receptor (PTGDR)." (PMID 27445529, 2016). "Tryptase and prostagladin D2 (PGD2) were chosen as major mast cell mediators, and more recently the PGD2 receptor gene (PTGDR) has been shown to be an asthma susceptibility gene." (PMID 15907205, 2005). "The previous studies on PTGDR were focused as an asthma susceptibility gene." (PMID 36368953, 2022). "Promoter variants have shown a different binding of transcription factors that controls the expression of PTGDR, and this could be related to the development of asthma susceptibility." (PMID 30986261, 2019). "In addition, epigenetic aspects of the PTGDR promoter have also been associated with asthma." (PMID 29088248, 2017). "In addition to these SNPs in PTGDR, the promoter polymorphism −731A>G and the intronic variant 6651C>T were found to be associated with asthma, atopic asthma, and bronchial hyperreactivity in families from UK, with similar results for 6651C>T in a Danish study." (PMID 27708579, 2016). "DP1 is a protein encoded by the PTGDR1 gene (also known as PTGDR) located at q22.1 on chromosome 14, a chromosomal site associated with asthma and other allergic diseases." (PMID 37915044, 2023). "There is evidence of an association of LTC4S, NOS2A, PTGDR, MET, COX-2, OSF-2, and LF polymorphisms and the risk of developing nasal polyps, especially when combined with chronic allergic rhinitis and asthma." (PMID 28400178, 2017). "Polymorphisms located in the promoter region of the Prostaglandin D Receptor (PTGDR) gene have been related to asthma." (PMID 29088248, 2017). "In that study the frequentist-based method identified two genes for asthma susceptibility (FRMD6 and PTGDR), while the BN-BMLA identified 3 additional genes." (PMID 23021489, 2012). "PTGDR is best known for their role in allergic diseases such as asthma." (PMID 39845197, 2025). "Evidence suggests that preventing the activation of the prostaglandin D2 receptor (DP2) pathway improves symptoms of asthma and pulmonary function, and impairs any change in eosinophil shape, while indirectly inducing a reduction in the number of exacerbations in severe asthmatic patients." (PMID 36140430, 2022). "For example, some studies have failed to associate two variants in PTGDR (−441C>T and −197TC>T) with asthma using family-based or case-control analyses in Latinos and African American asthmatics." (PMID 27708579, 2016). "Associations were confirmed between SNPs in PTGDR, PTGER2, MS4A2 and asthma." (PMID 22432035, 2012). "Earlier, in different association studies several asthma genes were identified in these regions, but none of them were confirmed later by GWAS, although two of them (PTGDR and GSTP1) were verified in candidate gene association studies in several independent populations." (PMID 22432035, 2012). "Previous work indicated that Tc2 cells express the prostaglandin D2 receptor CRTH229,30, which is in line with the increased abundance of CRTH2+CD4- T cells we detected in a different asthma patient cohort." (PMID 37612281, 2023).
asthma (continued). "In addition, particular PTGDR haplotypes could not be associated with Chinese children with asthma and atopy, or with two Australian populations of asthmatics, with similar data having been previously reported in a distinct Chinese population." (PMID 27708579, 2016). "We compared the gene expression levels of genes found to be relevant in asthma in the SNP analysis in sputum samples of 12 asthmatics and 9 controls using TaqMan Gene Expression Assays (FRMD6, PTGDR, PTGER2, MS4A2, AHNAK, PRPF19, TXNDC16)." (PMID 22432035, 2012). "Altogether 5 SNPs in 4 genes were found relevant in connection with asthma phenotype: PRPF19 on chromosome 11, and FRMD6, PTGER2 and PTGDR on chromosome 14." (PMID 22432035, 2012). "In the BN-BMLA analysis altogether 5 SNPs in 4 genes were found relevant in connection with asthma phenotype: PRPF19 on chromosome 11, and FRMD6, PTGER2 and PTGDR on chromosome 14." (PMID 22432035, 2012). "Additionally, the PTGDR diplotype (CCCT/CCC) was more frequent in patients with NP (p = 0.043), NP and asthma (p = 0.013), and with the aspirin triad (p = 0.041)." (PMID 28400178, 2017). "Therefore, the further study on the effect of metformin on PTGDR is urgent to be performed to identify whether PTGDR is the crosstalk target of T2DM and asthma." (PMID 36368953, 2022). "Targeting both PTGDR-1 and PTGDR-2 seems a valuable therapeutic approach to prevent flares in patients with SLE and in other diseases involving basophil, PGD2, and CXCL12 such as allergic diseases, chronic urticaria, asthma, inflammatory bowel diseases, and other chronic inflammatory disorders." (PMID 29463843, 2018). "The same authors also found that the PTGDR diplotype CCCT/CCCC (−613CC, −549CC, −441CC, and −197TC), with a potential influence on gene transcription, was more frequent in patients with nasal polyposis, with or without asthma, and in patients suffering from the aspirin triad." (PMID 27708579, 2016).
colorectal cancer (14 papers, 2015 to 2024). A primary or metastatic malignant neoplasm that affects the colon or rectum. "Hypermethylation of the selected markers (MAL, PRIMA1, PTGDR and SFRP1) can result in reduced gene expression and may contribute to the formation of colorectal cancer." (PMID 26482433, 2015).
colon cancer (11 papers, 2012 to 2024). "The HRM assays detected different levels of CpG methylation in the PTGDR promoter region in individual colon cancer samples." (PMID 23049694, 2012). "It is proposed that hypermethylation of PTGDR may make a contribution to reducing gene expression and developing colon cancer." (PMID 30186855, 2018). "It is found that the expression of PTGDR is lower in colon cancer." (PMID 30186855, 2018). "PTGDR has been negatively correlated with smoking and methylated in colon cancer, however, prior studies have not investigated its role in LUAD." (PMID 24369052, 2013).
allergic disease (8 papers, 2012 to 2025). An immune response that occurs following re-exposure to an innocuous antigen, and that requires the presence of existing antibodies against that antigen. "Different linkage and association studies have identified numerous genetic markers linked to allergic disease on chromosome 14, which include the PTGDR gene." (PMID 29088248, 2017). "Nevertheless, gene variants in the promoter region of PTGDR could lead to differences in expression regulation of this gene, which could be associated with an increased likelihood of developing allergic diseases." (PMID 29088248, 2017). "CRTH2 is a prostaglandin D2 receptor, and is a surface marker that is selectively expressed on, for instance, Th2 cells, but also on other cells involved in allergy, such as basophils and eosinophils." (PMID 29867934, 2018). "Our data corroborate the activation of IL4 in presence of PTGDR, which could have implications in allergic diseases." (PMID 30986261, 2019). "In conclusion, our results suggest that ATRA regulates the expression of PTGDR, which could be important in the regulation of Th1 and Th2 responses in allergic diseases." (PMID 30986261, 2019). "The correlation of in vitro expression and dyplotypic combinations in patients must be considered with caution, since other factors could influence the PTGDR expression and allergy development." (PMID 29088248, 2017). "However, new PTGDR-2 and dual PTGDR antagonists may achieve their clinical development in a near future and obtain approval in allergic disease treatment." (PMID 29463843, 2018). "A better understanding of the influence of PTGDR and ATRA on cytokine production can help to unravel molecular bases of allergic diseases, providing the field for better clinical interventions." (PMID 30986261, 2019). "The potent induction of PTGDR by ATRA and its inhibition by specific antagonists support that these effects are mediated through RAR receptors, pointing to RAR as a potential therapeutic target in allergic diseases." (PMID 30986261, 2019).
melanoma (8 papers, 2017 to 2025). A malignant, usually aggressive tumor composed of atypical, neoplastic melanocytes. "Mutation frequency of TBXAS1, PTGIS, AKR1C3, PTGDR, PTGFR and PTGER3 genes in melanoma were 5–6%, 5–7%, 2.8–5%, 3–4%, 7–9%, 2.1–5%, respectively." (PMID 35453789, 2022). "muTARGET web-based tool allowed us to predict genes, which expression patterns can be associated with genetic polymorphism in group #1 (TBXAS1, PTGIS, and AKR1C3) or group #2 (PTGDR, PTGFR, and PTGER3) in melanoma." (PMID 35453789, 2022).
adenoma (7 papers, 2012 to 2024). A neoplasm arising from the epithelium. "A recent report has shown that the PTGDR promoter is significantly methylated and associated with adenoma-carcinoma formation leading to CRC44." (PMID 30510283, 2018). "A set of transcripts (18 genes including MAL, SFRP1, SULT1A1, PRIMA1, PTGDR) showed decreasing expression (p < 0.01) in the biopsy samples along the adenoma-carcinoma sequence." (PMID 26482433, 2015). "In these independent sample sets, decreased PTGDR mRNA levels were found already in the adenoma samples, which further decreased in CRC samples." (PMID 23049694, 2012). "Our microarray results suggested that the PTGDR mRNA level decreases along the adenoma-carcinoma sequence on average." (PMID 23049694, 2012). "A tendentious PTGDR protein expression decrease was observed in the adenoma-carcinoma sequence progression." (PMID 23049694, 2012).
myocardial infarction (7 papers, 2017 to 2025). Gross necrosis of the myocardium, as a result of interruption of the blood supply to the area, as in coronary thrombosis. "The causal relationships revealed that NQO2 (1.047; 1.002–1.094; P = 0.042), CA6 (1.886; 1.015–1.162; P = 0.017), PTGDR (1.073; 1.012–1.137; P = 0.018), PTK2 (1.085; 1.002–1.176; P = 0.046), and CASP7 (1.080; 1.026–1.137; P = 0.003) were associated with high risk of myocardial infarction." (PMID 41573742, 2025).
prostate carcinoma (6 papers, 2007 to 2024). A carcinoma that arises from epithelial cells of the prostate gland. "Further studies are required to establish any relationships between prostate cancer progression and increased expression levels of PTGDR, GPR15, and GABRE genes." (PMID 17553164, 2007).
cholangiocarcinoma (4 papers, 2018 to 2023). A carcinoma that arises from the intrahepatic biliary tree (intrahepatic cholangiocarcinoma) or from the junction, or adjacent to the junction, of the right and left hepatic ducts (hilar cholangiocarcinoma). "A cfDNA analysis of cholangiocarcinoma patients and healthy sex- and age-matched controls revealed differentially methylated regions (DMRs) in four genes (HOXA1, PRKCB, CYP26C1, and PTGDR) in CCA patients." (PMID 37568696, 2023).
gastric tumor (4 papers, 2018 to 2024). "Among these genes, we further selected six GI hormone receptors whose expression was significantly down-regulated by 80–100% in the primary gastric tumors, including neuropeptide Y receptors (NPY1R and PPYR1), prostanoid receptors (PTGDR, PTGER2, and PTGER3), and a somatostatin receptor (SSTR2)." (PMID 30510283, 2018). "The qRT-PCR and bisulfite sequencing analyses of the six genes (NPY1R, PPYR1, PTGDR, PTGER2, PTGER3, and SSTR2) demonstrated a negative correlation between methylation and gene expression in two sets of paired gastric tumor and normal tissues." (PMID 30510283, 2018).
lupus (4 papers, 2018 to 2022). "Together, these data strongly suggested that PGD2 and PTGDR were associated with basophil activation and extravasation during lupus." (PMID 29463843, 2018). "Overall, we established a proof of concept that AMG853, a clinically relevant bispecific PTGDR-1 and PTGDR-2 antagonist, can control lupus-like inflammation in a manner similar to the combination of PTGDR-1- and PTGDR-2-specific antagonists." (PMID 35444641, 2022). "It will be of primary interest to determine in longer-term studies whether PTGDR blockade during the early stage of lupus-like nephritis prevents its development and could then be developed as a preventive therapy for SLE patients as well." (PMID 35444641, 2022). "Targeting PTGDR by specific antagonists inhibits basophil redistribution in SLO and dampens lupus-like disease both in Lyn−/− and in pristane-induced lupus models." (PMID 29463843, 2018). "Altering the crosstalk between these two axes in SLE patients using PTGDR-specific antagonists may break the basophil-dependent amplification of autoantibody production and kidney inflammation as it did in lupus-like mouse models." (PMID 29463843, 2018). "Here, we aimed at establishing a proof of concept that a clinically relevant bispecific antagonist of PTGDR-1 and PTGDR-2 could be efficient to treat murine lupus-like nephritis." (PMID 35444641, 2022). "Thus, bispecific PTGDR-1 and PTGDR-2 antagonists, such as AMG853, are a promising class of drugs for the treatment or prevention of organ damage in systemic lupus erythematosus." (PMID 35444641, 2022). "Here, we report that PGD2 induces a CXCR4-dependent accumulation of basophils in SLO, and that antagonizing PTGDR in vivo in two distinct lupus-like mouse models prevented this recruitment in SLO without impacting other cell type populations but the short-lived plasma cells." (PMID 29463843, 2018).
neuroblastoma (4 papers, 2012 to 2025). Neuroblastoma (NB) is the most common solid, extracranial childhood tumor. "In previous studies the methylation status of PTGDR was found to be correlated inversely with its expression in neuroblastoma cell lines." (PMID 23049694, 2012).
atopic dermatitis (2 papers, 2012 to 2013). "A stronger link of TSLP and disease can be found in patients with atopic dermatitis with an increase of TSLP level and increased frequency of human CD4+Th2 memory cells expressing the prostaglandin D2 receptor (CRTH2), suggesting TSLP may be involved in maintenance of Th2 memory pools." (PMID 23437132, 2013).
esophageal adenocarcinoma (1 paper, 2017). A malignant tumor with glandular differentiation arising predominantly from Barrett mucosa in the lower third of the esophagus. "FAT3 gene and PTGDR gene, both are shown to be associated significantly (p- value = 8.41E–04) with esophageal adenocarcinoma by IPA analysis." (PMID 28410234, 2017).
idiopathic pulmonary fibrosis (1 paper, 2022). Idiopathic pulmonary fibrosis (IPF) is a nonneoplastic pulmonary disease that is characterized by the formation of scar tissue within the lungs in the absence of any known cause. "It was reduced in lymphocytes in idiopathic pulmonary fibrosis, and the CCR5/prostaglandin D2 receptor CRTH2 ratio was also decreased in the T cells from SSc patients with ILD." (PMID 35216350, 2022).
Intestinal tumor (1 paper, 2014). "Homozygous deletion of the gene for PGD2 receptor PTGDR led to 30–40% more intestinal tumors in ApcMin/+ mice." (PMID 24729479, 2014). "The data support a role for PGD2 signals acting through PTGDR in suppression of intestinal tumors." (PMID 24729479, 2014).